TP53TG1 (TP53 target 1)
Diseases named in the same sentence as TP53TG1 in open-access papers (continued):
Sharing a sentence is not in itself a finding about the gene and the disease.
tumor (12 papers, 2018 to 2026). "We previously showed that tumor suppressor activity of TP53TG1 is linked to its ability to block the tumorigenic activity of the RNA binding protein YBX1." (PMID 34575588, 2021). "In the prognostic PRlncRNA risk model, 8 lncRNAs (HOTAIR, LINC00402, SFTA1P, LINC00461, DSCR8, CYP1B1-AS1, LINC00330, ALMS1-IT1) were upregulated, while the other 3 lncRNAs (ZRANB2-AS1, MYB-AS1, TP53TG1) were downregulated in tumor tissues." (PMID 35413978, 2022). "It has been described that TP53TG1 is shown to function diversely in either oncogenesis or tumor suppression in various tumors." (PMID 35661695, 2022). "Together, these results indicated that TP53TG1 plays a tumor suppressor role in the progression of Hela cells." (PMID 36267418, 2022). "In gastrointestinal cancer cells, TP53TG1 plays a tumor suppressive role through the sequestration of the RNA binding protein YBX1, thus blocking its oncogenic activity." (PMID 34564314, 2021). "Knockdown of TP53TG1 sensitized tumor cells to the antiproliferative effects of sorafenib." (PMID 36005829, 2022). "Moreover, simultaneous TP53TG1 overexpression and DDP treatment led to a more distinct inhibition on tumor growth, suggesting the promotive role of TP53TG1 on the sensitivity of NSCLC cells to cisplatin in vivo." (PMID 29588850, 2018).
TP53TG1 also shares sentences with these, for which no sentence is quoted: cutaneous melanoma (1 paper); genetic diseases (1); glomerulosclerosis (1); lung adenocarcinoma (1); lupus nephritis (1); lymph node metastasis (1); nasopharyngeal carcinoma (1); pancreatic cancer (1); pancreatic ductal adenocarcinoma (1).